COL1A1 (collagen type I alpha 1 chain)
Diseases named in the same sentence as COL1A1 in open-access papers (continued):
Sharing a sentence is not in itself a finding about the gene and the disease.
osteogenesis imperfecta (continued). "Additionally, the mutated COL1A1 gene in osteogenesis imperfecta was corrected using genome editing." (PMID 37109694, 2023). "Similarly, the expression of osteogenic signature genes was downregulated, including ALPL, an early marker of osteogenic differentiation, and COL1A1/2, two pathogenic genes for osteogenesis imperfecta." (PMID 37958322, 2023). "Osteogenesis imperfecta, characterized by increased bone fragility, may result from COL1A1 mutations." (PMID 37109694, 2023). "Interestingly, similar craniofacial abnormalities are seen in osteogenesis imperfecta, which is also caused by variants in COL1A1 or COL1A2 and can show clinical overlap." (PMID 36756177, 2023). "The two VUS were paternally inherited missense variants in the COL1A1 gene related to autosomal dominant forms of osteogenesis imperfecta (OMIM 166210) and paternally inherited nonsense variant in the COL10A1 gene related to autosomal dominant metaphyseal chondrodysplasia Schmid type (OMIM 156500)." (PMID 36360323, 2022). "Supporting our hypothesis, osteogenesis imperfecta caused by mutations in type I collagen genes (COL1A1/COL1A2) is associated with hemorrhagic diathesis, and is also hypothesized to be associated with vascular fragility." (PMID 34200258, 2021). "Genetic mutations in Col1a1 or Col1a2 genes (or other genes affecting Col1 biosynthesis) in humans lead to multiple subtypes of Osteogenesis Imperfecta (OI) syndrome, a bone disease referred to as the ‘brittle bone disease’3–5." (PMID 34893625, 2021). "Supporting our hypothesis, osteogenesis imperfecta caused by mutations in type 1 collagen genes (COL1A1/COL1A2) is associated with communicating hydrocephalus." (PMID 34425881, 2021). "On the other hand, for a patient who is highly suspected to have Osteogenesis Imperfecta (OI), a disease where large number of sequence variants in the COL1A1 and COL1A2 gene can be causative, a sequencing panel targeting those two genes would be most appropriate." (PMID 34071827, 2021). "The classical Sillence types of osteogenesis imperfecta (types I-IV), which comprise about 80-85% of cases, are inherited in an autosomal dominant manner caused by defects in the genes that encode type I collagen, COL1A1, and COL1A23." (PMID 34036147, 2021). "The two additional cases appeared with a combination of SNV and CNV affecting different genes and providing a dual diagnosis (neuronal ceroid lipofuscinosis type 3 plus C1q deficiency and COL1A1-related osteogenesis imperfecta plus Pitt-Hopkins-like syndrome type 2)." (PMID 32860008, 2021). "Supporting our hypothesis, osteogenesis imperfecta, that is caused by mutations in type 1 procollagen genes (COL1A1/COL1A2), is associated with communicating hydrocephalus." (PMID 32069308, 2020). "This is in agreement with other studies that have also found that complete COL1A1 deletion results in a clinical phenotype of mild osteogenesis imperfecta with increased susceptibility to fractures, variable short stature, blue sclerae, and minor, if any, skeletal deformities." (PMID 32281310, 2020). "Mutations affecting the carboxy-terminal-propeptide cleavage site of the type 1 procollagen chain (COL1A1) cause an unusual form of osteogenesis imperfecta in which individuals manifest marked bone fragility while having high BMD, due to hyperosteoidosis and hypermineralization." (PMID 33193107, 2020). "Approximately 90% of osteogenesis imperfecta cases are due to causative variants in the COL1A1 and COL1A2 genes, which result in abnormal collagen I fibrils formation, while the remaining 10% of cases are associated with recessive variants of known or yet to be discovered genes." (PMID 31299979, 2019). "More than 85% Osteogenesis Imperfecta (OI) patients have pathogenic variants in COL1A1/A2." (PMID 31568717, 2019). "COL1A1 mutations are one of the major causes of osteogenesis imperfecta." (PMID 27146865, 2016).
osteogenesis imperfecta (continued). "Following this example, I propose to define osteogenesis imperfecta as syndromes resulting from mutations in either COL1A1 or COL1A2 genes, and to group all other syndromes with congenital brittle bones as "syndromes resembling OI" (SROI), pending the identification of their causal mutation." (PMID 15339338, 2004). "Osteogenesis imperfecta (OI; brittle bone disease) is primarily caused by defects in COL1A1/2, but involves secondary TGF-β overactivity, contributing to bone fragility, growth deficiency, and blue sclerae." (PMID 41530114, 2026). "Osteogenesis Imperfecta (OI) is a heritable connective tissue disorder primarily caused by pathogenic variants in COL1A1 and COL1A2, encoding the pro-α chains of type I collagen." (PMID 41602857, 2026). "Osteogenesis Imperfecta (OI) is a genetic disorder caused by mutations in the COL1A1 or COL1A2 genes, leading to alterations in type I collagen." (PMID 40245284, 2025). "Osteogenesis Imperfecta (OI) is a rare genetic disorder characterized by defects in type I collagen synthesis due to mutations in the COL1A1 and COL1A2 genes, inherited in an autosomal dominant manner." (PMID 39797138, 2024). "Osteogenesis imperfecta (OI) is a rare genetic disorder commonly caused by variants of the type I collagen genes COL1A1 and COL1A2." (PMID 39012717, 2024). "Osteogenesis imperfecta (OI) is a rare genetic disorder of connective tissue, caused by inherited mutations of the genes COL1A1 or COL1A2 in approximately 90% of cases." (PMID 39767599, 2024). "Osteogenesis imperfecta (OI) is an inherited disorder characterized by bone fragility with extraskeletal manifestations mostly due to COL1A1 and COL1A2 variants." (PMID 39450342, 2024). "However, the mutation of COL1A1 in induced pluripotent stem cells (iPSCs) from osteogenesis imperfecta (OI) may result in bone fragility and repeated fractures." (PMID 37570352, 2023). "Osteogenesis imperfecta (OI) is a heritable connective tissue disorder caused by mutations in COL1A1 or COL1A2, leading to defective collagen synthesis and ECM organization, and is primarily studied in skeletal tissue." (PMID 37623368, 2023). "Osteogenesis imperfecta (OI) is a disorder with heterogeneous genetic causes that prominently include mutations in the type I collagen genes, COL1A1 and COL1A2." (PMID 37546916, 2023). "Osteogenesis imperfecta (OI) is a genetic disorder of connective tissue generally associated with pathogenic variants in COL1A1 or COL1A2 genes." (PMID 37375779, 2023). "The large majority of osteogenesis imperfecta (OI) arises from pathogenic variants in COL1A1 or COL1A2 which encode type 1 collagen." (PMID 37675393, 2023). "Osteogenesis imperfecta (OI) is the most common monogenic disease of the skeletal system and is usually caused by mutations in the COL1A1 or COL1A2 genes." (PMID 35804365, 2022). "Osteogenesis imperfecta (OI) is a rare inherited connective tissue dysplasia characterized with skeletal fragility, recurrent fractures and bone deformity, predominantly caused by mutations in the genes COL1A1 or COL1A2 that encode the chains of type I collagen." (PMID 35154279, 2022). "Osteogenesis imperfecta (OI) is a rare disorder of abnormal production or modification of type I collagen, which is caused by mutations in COL1A1, COL1A2 or other genes." (PMID 36339400, 2022). "Osteogenesis imperfecta (OI) is a group of rare genetic disorders caused mostly by pathogenic variants in the COL1A1 and COL1A2 genes, inherited in an autosomal dominant manner." (PMID 35893298, 2022). "The inherited brittle bone disease osteogenesis imperfecta (OI) is commonly caused by COL1A1 and COL1A2 mutations that disrupt the collagen I triple helix." (PMID 35701367, 2022). "The most prevalent heritable bone fragility disorder is osteogenesis imperfecta (OI) which is typically linked with autosomal dominant mutations in the COL1A1 or COL1A2 type I collagen alpha chain genes." (PMID 36497201, 2022).
osteogenesis imperfecta (continued). "Osteogenesis imperfecta (OI), a genetic disease caused by defective synthesis of type I collagen, is associated with mutations in the COL1A1 and COL1A2 genes." (PMID 34300306, 2021). "Osteogenesis imperfecta (OI) represents a complex spectrum of genetic bone diseases that occur primarily due to mutations and deletions of the COL1A1 and COL1A2 genes." (PMID 34946798, 2021). "Osteogenesis imperfecta (OI) is a rare disorder of bone fragility caused by mutations in the COL1A1/2 genes, which encode type I procollagen." (PMID 33859900, 2021). "Mutations in the collagen-I gene, COL1A1, result in various collagenopathies, most notably osteogenesis imperfecta (OI) and Ehlers-Danlos syndrome (EDS)." (PMID 33013490, 2020). "Osteogenesis imperfecta (OI) is an autosomal dominant form of osteoporosis most often caused by mutations in type I collagen genes (COL1A1, COL1A2)." (PMID 33066607, 2020). "Osteogenesis imperfecta (OI) is a heterogeneous group of disorders of connective tissue, caused mainly by mutations in the collagen I genes (COL1A1 and COL1A2)." (PMID 28498836, 2017). "Osteogenesis imperfecta (OI) is a remarkably heterogeneous monogenic disease characterized by bone fragility and low bone mass, more than 90% of which are caused by dominant mutations in encoding genes of type I procollagen chains proα1 (COL1A1, MIM 120150) or proα2 (COL1A2, MIM 120160)." (PMID 25238597, 2014). "Dominant mutations in COL1A1 or COL1A2 cause classical osteogenesis imperfecta (OI), with susceptibility to fractures from minimal trauma and growth deficiency." (PMID 24968150, 2014). "Osteogenesis imperfecta (OI) is a genetic disorder of MSC due to mutations in the COL1A1 and COL1A2 genes characterized by production of defective type I collagen, generalized osteopenia that leads to bone deformities and fractures in children." (PMID 23766767, 2013). "Osteogenesis Imperfecta (OI) is a heritable connective tissue disorder mainly caused by mutations in the genes COL1A1 and COL1A2 and is associated with hearing loss in approximately half of the cases." (PMID 22206639, 2011). "Osteogenesis imperfecta (OI) is a genetic disorder of connective tissue characterized by increased bone fragility and low bone mass due to mutations in the genes encoding type I collagen, particularly COL1A1 and COL1A2." (PMID 40171373, 2025). "Mutations in COL1A1 and COL1A2 genes can lead to osteogenesis imperfecta and congenital osteoporosis." (PMID 40832109, 2025). "Recent studies have identified specific COL1A1 and COL1A2 mutations that contribute to the severity of osteogenesis imperfecta, particularly in types I and III, highlighting the role of extracellular matrix proteins in skeletal homeostasis." (PMID 41153339, 2025). "This approach may be applicable for diseases such as osteogenesis imperfecta (OI), where OTIs show promise in correcting pathogenic point mutations in collagen genes like COL1A1 while avoiding off-target edits in wild-type alleles." (PMID 41188549, 2025). "Variants in COL1A1 and COL1A2, especially glycine-related missense variants, are classically associated with osteogenesis imperfecta (OI), a heritable disorder characterized by bone fractures, hearing loss, and dental impairments." (PMID 38892036, 2024). "COL1A1/2 osteogenesis imperfecta (COL1A1/2-OI), a genetic disorder primarily characterized by fractures resulting from minimal or no trauma, presents with a spectrum of clinical manifestations." (PMID 38392197, 2024). "Osteogenesis imperfecta (OI) is a rare genetic syndrome with autosomal dominant transmission due to a mutation of the COL1A1 and COL2A2 genes with consequent skeletal fragility and greater exposure to bone fractures; for this reason, it is also called brittle bone disease." (PMID 38786428, 2024).
osteogenesis imperfecta (continued). "Osteogenesis Imperfecta (OI), commonly defined as ‘brittle bones’ disease, is pathogenetically based on an hereditary collagen type I synthesis disorder, most often due to an autosomal dominant mutation in COL1A1 or COL1A2 genes." (PMID 38347577, 2024). "Mutations in COL1A1 and COL1A2 have profound implications, leading to osteogenesis imperfecta, a debilitating condition characterized by brittle bones and weakened connective tissues." (PMID 38384607, 2024). "Mutations in the COL1A1 and COL1A2 genes can lead to osteogenesis imperfecta inherited in an autosomal dominant manner." (PMID 38308345, 2024). "Mutations within the COL1A1 and COL1A2 genes, responsible for encoding type I collagen, can weaken connective tissue, leading to conditions such as osteogenesis imperfecta and Ehlers-Danlos syndrome." (PMID 38384607, 2024). "Mutations within genes encoding type I collagen, like COL1A1 and COL1A2, can result in conditions such as osteogenesis imperfecta and Ehlers-Danlos syndrome." (PMID 38384607, 2024). "Mutations in the type I collagen coding genes (COL1A1 and COL1A2) affecting collagen quantity or structure count for approximately 85% of osteogenesis imperfecta (OI) cases." (PMID 36923788, 2023). "Osteogenesis imperfecta (OI) is a rare inheritable skeletal disorder, caused, in most cases, by structural or quantitative defects in the α1 and α2 chains of collagen type I, encoded by COL1A1 or COL1A2 genes, respectively." (PMID 37643181, 2023). "Pathogenic variants in FGFR3, COL1A1, COL1A2, and COL2A1 are common causes of isolated short stature or osteogenesis imperfecta." (PMID 36923788, 2023). "In the case 2, 5 and 8, we found the WNT1or COL1A1-related VUS in osteogenesis imperfecta, and DYNC2H1 and NEK1-related asphyxiative hypoplasia of thorax." (PMID 37875969, 2023). "Osteogenesis Imperfecta (OI) is a connective tissue disorder caused by defects in genes encoding type I collagen (COL1A1 and COL1A2) or proteins responsible for synthesis, posttranslational modification and transport of collagen type I. This results in aberrant bone formation." (PMID 35546999, 2022). "In sheep, frameshift in OBSL1 has been shown to affect brachygnathia inferior, and mutations in COL1A1 and COL1A2 cause osteogenesis imperfecta." (PMID 35008901, 2022). "Mendelian disorders occurred more than once include Osteogenesis Imperfecta Type I (COL1A1, MIM:166200), Neurofibromatosis, Type I (NF1, MIM:162200) and Marfan Syndrome (FBN1, MIM:154700)." (PMID 35346302, 2022). "The most notable syndrome with dentin malformations as a phenotype is osteogenesis imperfecta (OI), which affects one in 15,000–20,000 births, with over 85% of cases being autosomal dominant OI types I-IV, caused by defects in COL1A1 and COL1A2, encoding type I collagen." (PMID 35627243, 2022). "Osteogenesis imperfecta (OI) is a genetic disorder characterized by increased bone fragility, low bone mass, and growth deficiency mostly caused by mutations in collagen type I encoding genes (COL1A1 and COL1A2)." (PMID 33925433, 2021). "For example, featured genes such as COL1A1, COL5A1, FN1, and ACTB are involved in invasive breast carcinoma and osteogenesis imperfecta, a heritable bone fragility disorder associated with short stature and abnormalities." (PMID 34858485, 2021). "Osteogenesis imperfecta (OI) is a clinically and genetically heterogeneous group of heritable disorders of connective tissue which is caused by dominant mutations in collagen type I, encoded by COL1A1 and COL1A2 in up to 90% of cases." (PMID 33743023, 2021). "Summary of the effects of substitution for glycine in lethal regions of the COL1A1 and COL1A2 gene with the number of mutations resulting in each type of Osteogenesis imperfecta." (PMID 34306033, 2021). "In the early 1980s, mutations in two genes of collagen type I (COL1A1 and COL1A2)were first associated with an autosomal dominant inheritance type of osteogenesis imperfecta." (PMID 33659802, 2020).
osteogenesis imperfecta (continued). "To date, the pathogenic genes of DGI type I, which is considered a clinical manifestation of syndrome osteogenesis imperfecta, include COL1A1 and COL1A2." (PMID 29575674, 2019). "Osteogenesis imperfecta (OI), also known as brittle bone disease, is a congenital bone disorder related to type 1 collagen alpha chains (COL1A1 and COL1A2) metabolism disorder that affects skeletal development." (PMID 29744175, 2017). "Mutations in the COL1A1 and COL1A2 genes are known to cause rare forms of Ehler’s Danlos Syndromes, types VIIA and B and osteogenesis imperfecta types I and II." (PMID 28346524, 2017). "In the current study, we conducted mutational analysis of the COL1A1 and COL1A2 genes among 91 Vietnamese patients with osteogenesis imperfecta." (PMID 27519266, 2016). "Mutations in COL1A1 and COL1A2 have implicated in the inheritance of osteogenesis imperfecta and have a relationship with bone mineral density in Chinese populations." (PMID 22808055, 2012). "Our study provides an example of paternal germline mosaicism in cattle as previously reported for achondrogenesis type II COL2A1‐related (OMIA001926‐9913), chondrodysplasia FGFR3‐related (OMIA001703‐9913) and osteogenesis imperfecta COL1A1‐related (OMIA002127‐9913)." (PMID 40525707, 2025). "These disorders are categorized into major clinical groups, such as Skeletal Dysplasias (e.g., analysis of genes like ACAN, ACP5, and ACVR1), Osteogenesis Imperfecta (COL1A1, COL1A2, BMP1), Metabolic Disorders (ACE, AGT, BICC1), and Cardiomyopathies, among others." (PMID 40282387, 2025). "Other COL1A1 variants are known to be associated with arthrochalasia-type EDS and osteogenesis imperfecta, but no COL1A1 variants have been associated previously with congenital diaphragmatic hernia or diaphragmatic rupture." (PMID 41356277, 2025). "Notably, mutations in the COL1A1 and COL1A2 genes, responsible for encoding type I collagen, are linked to rare genetic disorders like osteogenesis imperfecta and specific types of Ehlers-Danlos syndrome." (PMID 38384607, 2024). "Several missense variants were found, suggesting that the additive effects of pathological variants in COL1A1, COL1A2, and CERB3L1 may be necessary for osteogenesis imperfecta." (PMID 37762102, 2023). "This initial screening allowed us to identify families with osteogenesis imperfecta (caused by COL1A1 and COL1A2 mutations), as well as mutations in the non-repetitive regions of DSPP." (PMID 35627243, 2022). "We believe that the best genetic testing approach would be to obtain whole-exome sequencing (WES) of the proband′s genomic DNA, which would accurately identify pathological sequence variations in COL1A1 and COL1A2 that cause osteogenesis imperfecta (OI) and in the many genes causing AI." (PMID 35627243, 2022). "Osteogenesis imperfecta (OI), also known as brittle bone disease, is a disorder of connective tissue typically featured by fragile bones and susceptibility to fracture, mostly (~ 90%) caused by autosomal dominant pathogenic variants in the COL1A1 and COL1A2 genes, which encode type I collagen." (PMID 35463886, 2022). "In this case report, we reported a male infant with twenty-three intrauterine/fetal fractures resembling osteogenesis imperfecta and tested negative for COL1A1 and COL1A2 mutations." (PMID 34204301, 2021). "Aside from the pathogenic variants in COL1A1, COL1A2 and CREB3L1, we were unable to identify any other mutual variant related to collagen type I that could explain the phenotype with osteogenesis imperfecta and oligodontia." (PMID 32234057, 2020). "Next, GENOMOS embarked on studying COL1A1, a gene with long standing candidacy to be involved in the etiology of osteoporosis given its established effect on monogenic forms of skeletal fragility, i.e., osteogenesis imperfecta." (PMID 33162933, 2020).